RPUSD3 (RNA pseudouridine synthase D3)
Description:
Catalyzes uridine to pseudouridine isomerization (pseudouridylation) of specific mitochondrial mRNAs (mt-mRNAs), a post-transcriptional modification necessary for their translation. Acts at position 390 in COXI mt-mRNA and at position 697-699 in mitochondrial COXIII mt-mRNA. As a component of a functional protein-RNA module, consisting of RCC1L, NGRN, RPUSD3, RPUSD4, TRUB2, FASTKD2 and 16S mitochondrial ribosomal RNA (16S mt-rRNA), controls 16S mt-rRNA abundance and may play a role in mitochondrial ribosome biogenesis.
Synonyms: MGC29784
Tractability: PROTAC: ubiquitination databases record sites on it; its protein half-life has been measured.
Gene: Protein-coding gene on chromosome 3 (9,837,802 to 9,844,602, reverse strand). Ensembl gene ENSG00000156990.
Subcellular location: Mitochondrion matrix
Subcellular location (Human Protein Atlas): Nucleoplasm
Pathways (Reactome):
Metabolism of RNA: Mitochondrial mRNA modification; rRNA modification in the mitochondrion
Gene Ontology:
Molecular function: protein binding; RNA binding; tRNA pseudouridine synthase activity; pseudouridine synthase activity
Biological process: mRNA pseudouridine synthesis; positive regulation of mitochondrial translation; enzyme-directed rRNA pseudouridine synthesis; mRNA modification; pseudouridine synthesis; RNA modification
Cellular component: mitochondrial matrix; mitochondrion; ribonucleoprotein granule
Genetic constraint (gnomAD): Loss-of-function variants: 40 observed, 39.05 expected, observed/expected ratio (o/e) 1.02, 90% interval 0.79 to 1.33. The upper end of that interval is the gene's LOEUF score, 1.33, which puts it in group 5 of 6, group 1 being the genes least tolerant of losing a copy. Missense variants: 486 observed, 458.07 expected, observed/expected ratio (o/e) 1.06, 90% interval 0.98 to 1.14. Synonymous variants: 202 observed, 195.31 expected, observed/expected ratio (o/e) 1.03, 90% interval 0.92 to 1.16.
Homologues: Orthologues: chimpanzee RPUSD3 (98% identical), macaque RPUSD3 (83% identical), pig RPUSD3 (82% identical), dog RPUSD3 (81% identical), mouse Rpusd3 (73% identical), rat Rpusd3 (69% identical), guinea pig RPUSD3 (68% identical), tropical clawed frog rpusd3 (44% identical), Caenorhabditis elegans ZK287.7 (17% identical). Paralogues in human: RPUSD4 (26% identical), RPUSD2 (18% identical), RPUSD1 (18% identical).
Diseases named in the same sentence as RPUSD3 in open-access papers:
RPUSD3 is named in the same sentence as 4 diseases in open-access papers, as found by Europe PMC text mining. Sharing a sentence is not in itself a finding about the gene and the disease. The quoted sentences say what the papers report.
glioma (1 paper, 2021). A benign or malignant brain and spinal cord tumor that arises from glial cells (astrocytes, oligodendrocytes, ependymal cells). "Six Ψ synthase genes were associated with the prognosis, of which the expression of PUS1, PUS7, RPUSD1 and RPUSD3 was positively associated with the malignancy of glioma (HR > 1), and TRUB1 was negatively associated with the malignant grade (HR < 1)." (PMID 35118063, 2021).
Sepsis (1 paper, 2023). Sepsis is defined as life-threatening organ dysfunction caused by a dysregulated host response to infection. "For instance, genes mediating RNA Ψ modification (TRUB1, TRUB2, PUS1, RPUSD3, RPUSD4, PUS7, RPUSD2) were mainly suppressed in sepsis." (PMID 37701433, 2023).
tumor (2 papers, 2022 to 2026). "RPUSD3 expression was negatively correlated with both stromal and immune scores and positively correlated with tumor purity." (PMID 36437949, 2022). "The results suggest that PUS family members, including PUS1, RPUSD1, RPUSD3, and PUS7, may contribute to both enhanced tumour stemness and the establishment of an immunosuppressive microenvironment in PAAD." (PMID 41496500, 2026). "Similar to RPUSD3, the expression of PUS7 may also imply higher tumor purity." (PMID 36437949, 2022).
RPUSD3 also shares sentences with these, for which no sentence is quoted: prostate adenocarcinoma (1 paper).